RUNX3 (RUNX family transcription factor 3)
Diseases named in the same sentence as RUNX3 in open-access papers (continued):
Sharing a sentence is not in itself a finding about the gene and the disease.
Limb ataxia (5 papers, 2013 to 2026). A kind of ataxia that affects movements of the extremities. "In mice, Runx1 knockout abolishes definitive haematopoiesis, Runx2 deficiency impairs bone formation, and Runx3 loss leads to limb ataxia due to neuronal death during embryogenesis." (PMID 41550415, 2026). "In Runx3-deficient mice, TrkC neurons are generated but fail to extend central and peripheral afferents, leading to neuronal death and limb ataxia." (PMID 39715266, 2024). "Runx3 is expressed in TrkC neurons via the P2 promoter, and similarly to Runx3-deficient mice, P2-/- mice also develop severe limb ataxia." (PMID 39715266, 2024). "Runx3-deficient mice develop severe limb ataxia due to TrkC neuron cell death." (PMID 39715266, 2024). "In addition, Runx3-deficient mice display severe motor discoordination and limb ataxia." (PMID 23418536, 2013). "The survival and/or specification of the TrkC-positive proprioceptive afferents also requires the expression of the Runt-related transcription factor 3 (Runx3) and Runx3-knockout mice display severe limb ataxia due to absence of proprioceptive sensory neurons." (PMID 33407830, 2021). "Moreover, RUNX3 is involved in sensory neuron differentiation and has been shown to regulate the axonal projection of proprioceptive dorsal root ganglion (DRG) neurons—Runx3 KO mice showed severe limb ataxia and abnormal posture." (PMID 36766749, 2023).
lung adenoma (5 papers, 2014 to 2022). A benign, well circumscribed epithelial neoplasm that arises from the bronchus or the lung parenchyma. "Lee’s work has shown that Runx3+/− mice spontaneously acquired lung adenomas around 18 months of age, whereas Runx3−/− mice died from lung epithelial hyperplasia soon after birth." (PMID 36429115, 2022). "Runx3 targeted deletion in mouse lung resulted in lung adenomas and abrogated the cellular defense mechanism against oncogenic activation, suggesting that Runx3 plays critical roles in normal differentiation and suppression of tumor initiation." (PMID 26375442, 2015). "RUNX3 suppresses the development of lung adenoma in the setting of activated KRAS, and this effect is mediated by RUNX3-induced expression of p14ARF and p21WAF/CIP." (PMID 24722523, 2014). "If K-Ras activation alone does not induce lung adenoma, but Runx3 inactivation does, how can lung adenoma develop in a mouse model in which K-Ras is activated alone?" (PMID 25961920, 2016).
oral cancer (5 papers, 2012 to 2022). "We speculated that the early dissemination and metastasis of OSCC may be related to the driving mutations such as SMARCA4, CXCR4 and RUNX3, which provides a theoretical basis for the future study on the mechanism of early spread and metastasis of oral cancer." (PMID 36424557, 2022). "The emerging role of RUNX3-mediated perturbation of the canonical Wnt signaling pathway in oral cancers also needs to be further evaluated." (PMID 22645611, 2012). "Given our results that the expression of miR-145-5p and RUNX3 was reduced by PDT, we could extrapolate that miR-145-5p and RUNX3 may also act as oncogene in oral cancer." (PMID 28456786, 2017). "To investigate the mechanism by which RUNX3 expression in OSCC cells could cause osteolysis, we focused on the role of RUNX3 and TGF-β in the interactions between oral cancer and the bone microenvironment." (PMID 28030842, 2017). "The increased RUNX3 gene expression in the most advanced tumor stage, stage IV, with bone invasion is consistent with our in vitro and in vivo data suggesting the oncogenic role of RUNX3 in oral cancer bone invasion." (PMID 28030842, 2017). "Other groups have reported that reduced RUNX3 expression or promoter hypermethylation is associated not only with progression in oral cancers, but also with disease recurrence and poorer prognoses." (PMID 22645611, 2012). "The fact that other groups have not found significant associations between RUNX3 promoter hypermethylation and patient outcomes suggests that the role of epigenetic silencing of this gene in oral cancers bears further scrutiny." (PMID 22645611, 2012). "However, the role of RUNX3 in bone invasion via interactions between oral cancer and the bone microenvironment remains unclear." (PMID 28030842, 2017). "To understand the mechanism why miR-145-5p expression enhances PDT efficacy in oral cancer cells, we attempted to see whether miR-145-5p can bind to RUNX3, which was found to be a biomarker to determine the sensitivity of PDT effect in OSCC in our previous study." (PMID 28456786, 2017). "RUNX3 alone or in combination with TGF-β and PTHrP may be a useful predictive biomarker and therapeutic target for bone invasion by oral cancer." (PMID 28030842, 2017). "RUNX3 independently or in combination with TGF-β and PTHrP may serve as a biomarker for predicting the prognosis of and potential for bone invasion in oral cancer patients, and it may also serve as a potential therapeutic target for controlling cancer invasion." (PMID 28030842, 2017).
oral squamous cell carcinoma (5 papers, 2011 to 2019). "The methylation of DACH1, DKK1, LKB1, PPP2R2B, RUNX3, SFRP2, and WIF-1 was analyzed in 16 oral squamous cell carcinoma cell lines using the methylation-specific polymerase chain reaction." (PMID 25487617, 2015). "In the first stage, 16 oral squamous cell carcinoma cell lines were screened for the methylation of DACH1, DKK1, LKB1, PPP2R2B, RUNX3, SFRP2, and WIF-1 using methylation-specific PCR." (PMID 25487617, 2015).
autoimmune disease (4 papers, 2013 to 2024). A disorder resulting from loss of function or tissue destruction of an organ or multiple organs, arising from humoral or cellular immune responses of the individual to their own tissue constituents. "It is obvious that RUNX3 is not only a tumor suppressor but also plays an important role in autoimmune diseases and inflammations." (PMID 23637848, 2013).
celiac disease (4 papers, 2013 to 2022). An autoimmune genetic disorder with an unknown pattern of inheritance that primarily affects the digestive tract. "Of note, the human homologs of four of the CD11b+ DC Runx3 targets, CD300LF, IFIH1, IRF4 and SLC22A5 (mouse Slc22a21) harbored SNPs associated with IBD, CD, UC and/or celiac disease and the two former genes are common Runx3 targets in RM and CD11b+ DC." (PMID 32453801, 2020). "Ten of these cDC2 high-confidence Runx3 targets were common to those in RM and human homologs of four, CD300LF, IFIH1, IRF4 and SLC22A5 (mouse Slc22a21) harbored SNPs associated with IBD, CD, UC and/or celiac disease." (PMID 32453801, 2020).
lymph node metastasis (4 papers, 2008 to 2022). "The analysis identified lymph node metastasis, invasion of retroperitoneal tissue, and hypermethylation of RUNX3 gene as the variables for independently predicting overall survival." (PMID 18475302, 2008).
metastatic tumors (4 papers, 2008 to 2019). "In brief, KPC (SMAD4(+/+)) and KPDDC (SMAD4(−/−)) tumors showed increased RUNX3 expression levels and a high metastatic disease burden, and the high expression of RUNX3 was associated with increased metastatic potential of PDACs independent of epithelial-mesenchymal transition." (PMID 29100342, 2017). "While 11/14 (78.6%) of the cases showed concordant SMAD4 expression status between the matched primary and metastatic tumors, only 6/14 (42.9%) cases showed concordant RUNX3 expression status." (PMID 29100342, 2017). "When comparing methylation rates in localized tumors versus metastatic disease, the methylation of RUNX3 (p = 0.013), SCGB3A1-2 (p = 0.008), SFRP4-2 (p = 0.022), and DLC1 (p = 0.016) was significantly associated with the presence of metastatic disease." (PMID 20849603, 2010). "Methylation of RUNX3, SCGB3A1, SFRP4, and DLC1 was significantly associated with the extent of the disease when comparing localized versus metastatic tumors." (PMID 20849603, 2010). "We next examined Runx3 expression in metastatic tumors using immunostaining." (PMID 31122259, 2019). "In addition, all RUNX3-discordant cases showed conversion from RUNX3-positivity in the primary tumor to RUNX3-negativity in the matched metastatic tumors." (PMID 29100342, 2017). "Thus, it may be hypothesised that there is indeed loss of RUNX3 expression by promoter hypermethylation or LOH in some primary tumours compared with normal islets, and almost a complete loss in metastatic tumours." (PMID 18475302, 2008). "Biopsies or resected tissues from metastatic sites were available for 14/121 patients and the whole tissue sections of the 14 metastatic tumors were subjected to SMAD4 and RUNX3 immunohistochemistry." (PMID 29100342, 2017). "Identical RUNX3/SMAD4 profiles were seen in the primary and metastatic tumors of 5/14 (35.7%) cases." (PMID 29100342, 2017). "All primary tumors showed RUNX3 expression and/or SMAD4 loss; RUNX3-/SMAD4+ status was not seen in any of the primary or metastatic tumors in this analysis." (PMID 29100342, 2017). "Interestingly, out of the 14 matched cases, the RUNX3-/SMAD4+ profile was seen in none of the primary PDACs and also in none of their subsequent metastatic tumors." (PMID 29100342, 2017). "In addition, only 1/14 (7.1%) of the metastatic tumors had intact SMAD4 expression, and all 8 (100%) cases with discordant RUNX3 status were RUNX3+ in the primary tumor and RUNX3-negative in the matched metastatic tumors." (PMID 29100342, 2017).
multiple sclerosis (4 papers, 2013 to 2024). A progressive autoimmune disorder affecting the central nervous system resulting in demyelination. "All genes were downregulated in expression except RUNX3, which was upregulated in type 1 diabetes, and CYBB in multiple sclerosis." (PMID 38956704, 2024).
osteoarthritis (4 papers, 2022 to 2024). A noninflammatory degenerative joint disease occurring chiefly in older persons, characterized by degeneration of the articular cartilage, hypertrophy of bone at the margins and changes in the synovial membrane. "Runx2 is an important pathogenic factor, while Runx1, Runx3, and Cbfb are protective factors in osteoarthritis development." (PMID 39337587, 2024). "Three out of the 166 enriched RBPs (PRDM1, RUNX3 and PPARG) were also DE in our dataset and have been extensively linked to osteoarthritis." (PMID 35088088, 2022). "Runx3-knockout mice exhibited accelerated osteoarthritis following surgical induction, accompanied by decreased expression of lubricin and aggrecan." (PMID 36261443, 2022). "Intra-articular administration of Runx3 adenovirus ameliorated development of surgically induced osteoarthritis." (PMID 36261443, 2022). "Here, we examined the role of Runx2 and Runx3 for osteoarthritis development in vivo and in vitro." (PMID 36261443, 2022). "Possible distinct contributions of Runx 2 and Runx3 in osteoarthritis have not been clarified." (PMID 36261443, 2022).
Osteopenia (4 papers, 2019 to 2024). Osteopenia is a term to define bone density that is not normal but also not as low as osteoporosis. "The Runx3-deficient mice develop severe congenital osteopenia, and the rs6600247 AS risk allele, located in an enhancer-like region upstream of the RUNX3 promoter, modulates c-MYC binding." (PMID 36803548, 2023). "Therefore, the cryptic Runx2 protein may reduce bone mass by inhibiting the binding of Runx3, because the deletion of Runx3 in osteoblasts using the 2.3-kb Col1a1 promoter Cre transgenic mice results in osteopenia." (PMID 30987410, 2019).
pancreatic ductal adenocarcinoma (4 papers, 2017 to 2023). An infiltrating adenocarcinoma that arises from the epithelial cells of the pancreas. "While RUNX3 can inhibit proliferation, highly elevated levels of RUNX3 in pancreatic ductal adenocarcinoma can direct a metastatic program to promote cell migration, invasion and distant colonization." (PMID 34831147, 2021). "Moreover, RUNX3 was shown to function as both tumor suppressor and tumor promoter in pancreatic ductal adenocarcinoma." (PMID 34831147, 2021). "SMAD4/DPC4 mutations have been associated with aggressive behavior in pancreatic ductal adenocarcinomas (PDAC), and it has recently been suggested that RUNX3 expression combined with SMAD4 status may predict the metastatic potential of PDACs." (PMID 29100342, 2017).
rectal cancer (4 papers, 2014 to 2025). A primary or metastatic malignant neoplasm that affects the rectum. "RUNX3 was significantly associated with rectal cancer survival, while BMP1 (PARTP = 0.099) and BMPR1A (PARTP = 0.085) were marginally significant." (PMID 25541970, 2014). "Seven genes (IL2RA, IL8RA, IL8RB, IRF2, RAF1, RUNX3, and SEPX1) were significantly associated with rectal cancer (PARTP<0.05)." (PMID 25541970, 2014). "In 2012, Jo and colleagues used methylation specific PCR to examine a panel of 5 CIMP markers (i.e., CACNA1G, IGF2, NEUROG1, RUNX3, and SOCS1) in rectal cancer patients receiving 5-FU-based neoadjuvant chemoradiation." (PMID 31390840, 2019). "This article investigated whether Runt-Related Transcription Factor 3 (RUNX3) and enhancer of zeste homolog 2 (EZH2) can be used to evaluate the clinical efficacy of neoadjuvant therapy and prognosis of locally advanced rectal cancer (LARC)." (PMID 35280723, 2022).
viral infections (4 papers, 2018 to 2022). "We next examined the impact of MAZR- and/or Runx3-deficiency on CTL differentiation in vivo upon acute viral infection." (PMID 33815354, 2021). "RUNX3 is known to be activated upon some viral infections, indicating functional relevance of these links." (PMID 33163005, 2020). "In conclusion, this study shows that Runx3 and ThPOK cross-regulate the acquisition of cytotoxic function by Th1 lymphocytes and therefore represent targets for interventions against viral infections, cancer and autoimmune disorders." (PMID 29488879, 2018). "In pulmonary diseases, RUNX3 induces the apoptosis of airway epithelial cells on viral infections." (PMID 36479199, 2022).
allergic asthma (3 papers, 2009 to 2019). A asthma with a basis in a pathological type I hypersensitivity reaction. "In mice, loss of RUNX3 function results in an allergic asthma phenotype due to accelerated dendritic cell maturation and resulting increased efficacy to stimulate T cells." (PMID 19714205, 2009). "Here we report that mice lacking Bcl11b in mature T-cells have a diminished capacity to mount Th2 responses during helminth infection and allergic asthma, showing reduced Th2 cytokines and Gata3, and elevated Runx3." (PMID 29700302, 2018).
Ataxia (3 papers, 2017 to 2024). Ataxia refers to impaired coordination of voluntary muscle movement. "Deletion of Runx3 in neurons (Wnt1-Cre/Runx3f/f;) recapitulated the ataxia phenotype that occurred in Runx3-deficient mice, and was associated with severe skeletal scoliosis." (PMID 39715266, 2024). "RUNX3 appears to have an important role in the development of proprioceptive afferent neurons in mice, resulting in ataxia, a neurological finding that is not uncommon in ASD." (PMID 29312285, 2017).
cytomegalovirus infection (3 papers, 2020 to 2025). A herpesvirus infection caused by Cytomegalovirus. "Runx3 is also required for the differentiation and local expansion of NK cells in response to mouse cytomegalovirus infection, which was demonstrated by using NK cell-specific Runx3 KO mouse model." (PMID 36275778, 2022). "A similar crossregulation of RUNX3 and ThPOK was also observed during the acquisition of cytotoxic function by human Th1 lymphocytes in the context of human cytomegalovirus infection." (PMID 32102981, 2020). "Similarly, Runx3 is also required for the differentiation and local expansion of NK cells in response to mouse cytomegalovirus infection, which was demonstrated in NK cell-specific Runx3 KO mice." (PMID 36275778, 2022). "Decondensation of L1 through this mechanism could facilitate the binding of L1 transcriptional activators, such as RUNX3 and YY1, whose expression we previously observed to increase upon HCMV infection, further promoting L1 expression." (PMID 40267069, 2025).
diabetes (3 papers, 2013 to 2022). "We therefore speculate that REG1A causes diabetes by destroying islet cells, whereas RUNX3 causes DKD by directly destroying vascular endothelial cells." (PMID 35937821, 2022). "Although there are no reports on relationships between Runx3 and diabetes, or between Runx3 and EPCs, our study shows that Runx3 is expressed by EPCs, and increased Runx3 in EPCs of type II DM patients due to downregulated miR-130a causes EPC dysfunction." (PMID 23874686, 2013).
gallbladder cancer (3 papers, 2024 to 2025). "DNA methyltransferase 1 (DNMT1) can mediate methylation of RUNX3 to down-regulate RUNX3 in gallbladder cancer cells." (PMID 40959280, 2025). "The expression of RUNX3 is notably diminished in gallbladder cancer tissues and cells, largely attributed to DNA Methyltransferase 1 (DNMT1)-mediated methylation." (PMID 38430423, 2024).
gastric adenocarcinoma (3 papers, 2011 to 2023).